STAT3 (signal transducer and activator of transcription 3)
Diseases named in the same sentence as STAT3 in open-access papers (continued):
Sharing a sentence is not in itself a finding about the gene and the disease.
nasopharyngeal carcinoma (continued). "STAT3 activity is a well-established player in cancer stemness and, indeed, CD24-induced STAT3 activation in nasopharyngeal carcinoma cells triggers their reprogramming towards a CSC state." (PMID 28320418, 2017). "For example, up-regulation of ΔNp63 was correlated with the activation of STAT3 in human nasopharyngeal carcinoma cells." (PMID 27391430, 2016). "Latent membrane protein 1 (LMP1) and IFN-γ upregulate PD-L1 through STAT3, AP-1, and NF-κB pathways, which promotes progression of nasopharyngeal carcinoma (NPC) and ovarian cancer." (PMID 26305724, 2015). "We demonstrated IL-6 modulated iNOS expression via STAT3 and EGFR in EBV-associated nasopharyngeal carcinoma." (PMID 25547488, 2014). "Recently, it has been reported that STAT3 activation contributes directly to the invasiveness of nasopharyngeal cancer cells." (PMID 23382914, 2013). "Some report showed that cucurbitacin I can inhibit migration of keloid fibroblasts and also reduces the invasiveness of nasopharyngeal carcinoma cell lines with elevate STAT3 activation." (PMID 23393598, 2013). "The CENPN/STAT3/USP37 axis is expected to be a new target for nasopharyngeal carcinoma treatment." (PMID 40458725, 2025). "API was shown to reduce levels of p-EGFR, p-Akt, and p-Stat3 in nasopharyngeal carcinoma." (PMID 38263290, 2024). "Additionally, OIP5 KD has been observed to inhibit epithelial–mesenchymal transition (EMT) and downregulate phosphorylated JAK2 and phosphorylated STAT3 in the JAK2-STAT3 pathway in nasopharyngeal carcinoma." (PMID 38474305, 2024). "The upregulation of miR-124 has also been associated with reduced proliferation, migration, and invasion of nasopharyngeal carcinoma cells (C666-1 cells) via downregulation of STAT3, p-STAT3, G1/S-specific cyclin-D2 (CCND2) and Matrix Metalloproteinase-2 (MMP-2) expression in C666-1 cells." (PMID 36936170, 2023). "STAT3 activation was inhibited in the nasopharyngeal carcinoma cells." (PMID 36675232, 2023). "In addition, knocking out CKMT1 decreased STAT3 phosphorylation, thus increasing the radiosensitivity in Nasopharyngeal carcinoma therapy." (PMID 37061730, 2023). "Previous research revealed that OIP5 could promote metastasis of nasopharyngeal carcinoma cells by promoting EMT via modulation of JAK2/STAT3 signal." (PMID 35242130, 2022). "So we detected the expressions of AKT and STAT3 in nasopharyngeal carcinoma CNE-2Z cells." (PMID 33390776, 2021). "It is suggested that AKT/STAT3 signaling could be identified as the potential therapeutic target of oridonin against nasopharyngeal carcinoma." (PMID 33390776, 2021). "Also in another EBV-associated tumor, the nasopharyngeal carcinoma (NPC), the EBV-induced latent membrane protein 1 (LMP1) and IFNγ, upregulated PD-L1 expression through AP-1, STAT3 and NF-κB pathways." (PMID 31340499, 2019). "Indeed, in a previous study, CCB induced apoptosis by inhibiting the expressions of p-STAT3 and Mcl-1 in nasopharyngeal carcinoma cells." (PMID 29541415, 2018). "Furthermore, studies on nasopharyngeal cancer have suggested that AA may interact with the STAT3 pathway by inhibiting STAT3 phosphorylation." (PMID 38610995, 2024). "In nasopharyngeal carcinoma cells (NPCs), β-elemene inhibits DNA damage repair and NPC cell growth via inactivation of Stat3 and reduces DNMT1 and EZH2 expression." (PMID 37121970, 2023). "Berberine exerted inhibitory effects on constitutive and IL-6-triggered activation of STAT3 in NPC (nasopharyngeal carcinoma) cells." (PMID 30987378, 2019). "It has been reported to inhibit nasopharyngeal carcinoma (NPC) CSCs through attenuation of STAT3 or NF-κB p65 activity." (PMID 28156178, 2017). "Epstein-Barr virus-encoded microRNA nasopharyngeal carcinoma BART1 induces tumour metastasis by regulating PTEN-dependent pathways in NPC while miR-23 targets IL-8/Stat3 pathway sensitizing NPC cells to irradiation." (PMID 27589832, 2016).
nasopharyngeal carcinoma (continued). "Our previous studies have revealed that EGFR mutations could up-regulate the expression of PD-L1 via p-ERK1/2/p-c-Jun pathways, while LMP-1, an important oncogene in nasopharyngeal carcinoma could also induce the expression of PD-L1 through STAT3, AP-1, and NF-κB pathways." (PMID 26361045, 2015). "In this study, we have examined the effects of berberine on tumorigenicity and growth of nasopharyngeal carcinoma (NPC) cells and their relationship to STAT3 signaling using both in vivo and in vitro models." (PMID 24380387, 2013). "Similar signaling pathways have been observed in tumor cells, where FLOT2 upregulates CD109 by stabilizing the expression of STAT3, inhibiting the TGF-β signaling pathway and promoting the development of nasopharyngeal carcinoma." (PMID 41327642, 2025). "Reduced PTPRD expression has been reported in nasopharyngeal carcinoma (NPC), whereas increased PTPRD levels enhance the sensitivity of NPC cells to radiotherapy by decreasing STAT3 phosphorylation." (PMID 40166646, 2025). "We first performed immunofluorescence staining of 5-8F cells to explore the detailed molecular mechanism by which CENPN promotes nasopharyngeal carcinoma metastasis, and the results revealed that CENPN and STAT3 were colocalized." (PMID 40458725, 2025). "The expression of CENPN, STAT3 and USP37 in metastatic tumors from nude mice and human nasopharyngeal carcinoma tissues was verified by immunohistochemistry and immunofluorescence staining." (PMID 40458725, 2025). "CENPN directly binds to STAT3 and promotes STAT3 phosphorylation and nuclear translocation to regulate USP37 transcription, thus promoting the invasion and metastasis of nasopharyngeal carcinoma." (PMID 40458725, 2025). "AGK was also considered to be a promoter of resistance to paclitaxel in nasopharyngeal carcinomas and this chemoresistance properties which eventually mediate tumor growth and metastasis is facilitated by overexpressed FOXM1 via JAK2/STAT3 signaling pathway." (PMID 40176914, 2025). "Furthermore, EBV‐induced latent membrane protein 1 (LMP1) upregulates PD‐L1 in nasopharyngeal carcinoma (NPC) through STAT3, AP‐1 and NF‐κB pathways." (PMID 36515567, 2023). "Phosphorylation of EphA2 at S897 mediates the activation of the AKT, STAT3, SOX-2, and c-MYC signaling pathways, which is crucial to nasopharyngeal carcinoma stem cell formation." (PMID 37063424, 2023). "Studies have shown that EphA2 pS897 activates the AKT, STAT3, SOX-2, and c-MYC signaling pathways and plays a crucial role in nasopharyngeal carcinoma stem cell formation." (PMID 37063424, 2023). "It is also essential to balance the benefits between increased LMP1 levels via the NF-κB and STAT3 pathways and PDT efficiency in killing nasopharyngeal carcinoma cells (>70%)." (PMID 37239013, 2023). "A high STAT3 expression correlates with a better clinical outcome in patients with CRC and nasopharyngeal carcinoma." (PMID 36061181, 2022). "In nasopharyngeal carcinoma cells, SFN inhibits growth through the DNMT1/Wnt inhibitory factor 1 (WIF1) axis, as well as inhibits total STAT3 oncogene expression level and STAT3 phosphorylation (troy 704 and troy 705) by upregulation of miRNA-124-3p." (PMID 35052539, 2021). "Our results revealed that oridonin inhibits nasopharyngeal carcinoma cell migration and invasion, and reverse EMT via the inactivation of AKT/STAT3 signaling pathway." (PMID 33390776, 2021). "Their study demonstrated that DANCR, acting as an oncogene in nasopharyngeal carcinoma, promoted nasopharyngeal carcinoma progression by interacting with STAT3 and enhancing JAK1 binding to STAT3 to strengthen IL-6/JAK1/STAT3 signaling." (PMID 33123287, 2020). "Berberine also suppresses the invasive and metastasis of nasopharyngeal carcinoma (NPC) by inhibiting the activation of Signal Transducer and Activator of Transcription 3 (STAT3), a key mediator to trigger tumor-promoting inflammation." (PMID 28702078, 2017).
nasopharyngeal carcinoma (continued). "In prostate cancer cells and in nasopharyngeal carcinoma, high IL-8 expression confers radioresistance, mediated, in nasopharyngeal cancer, by PI3 kinase and Stat3-dependent signaling pathways." (PMID 27500125, 2016). "Nuclear accumulation of epidermal growth factor receptor (EGFR) and activation of STAT3 by IL-6 play a key role in iNOS expression and resultant DNA damage, leading to EBV-related nasopharyngeal carcinoma." (PMID 25547488, 2014). "Pertinently, PTPRD is downregulated in nasopharyngeal carcinoma (NPC), and PTPRD overexpression can promote the sensitivity of NPC cells to radiotherapy owing to STAT3 dephosphorylation." (PMID 35356799, 2022). "In addition, the inhibition of STAT3 sensitizes HNSCC to chemotherapy and radiotherapy, particularly nasopharyngeal carcinoma (NPC)." (PMID 36291769, 2022). "However, whether AKT/STAT3 signaling pathway was involved in the oridonin-mediated MET in nasopharyngeal carcinoma has not been clarified." (PMID 33390776, 2021). "For example, in nasopharyngeal carcinoma, lncRNA differentiation antagonizing nonprotein coding RNA (DANCR) can interact with STAT3 to enhance JAK1 binding to STAT3." (PMID 34425834, 2021). "An earlier study has examined the relationship of LMP1 expression and STAT3 activation in nasopharyngeal carcinoma using immunocytochemistry but failed to reveal a positive correlation of LMP1 expression and STAT3 activation." (PMID 23658720, 2013).
head and neck cancer (106 papers, 2002 to 2025). A primary or metastatic malignant neoplasm affecting the head and neck. "Cigarette smoke has also been associated with increased STAT3 phosphorylation in several cancer types, including head and neck cancer." (PMID 40140827, 2025). "Recently, the number and function of Foxp3+ Tregs have been reported to be associated with STAT3 expression level, and STAT3 was simultaneously regarded as an potent therapeutic target for Tregs in head and neck cancer." (PMID 36226375, 2023). "Of note, HPV-related cancers, including cervical and head and neck cancers, often showed hyperactivated STAT3 due to virus-associated inflammatory responses." (PMID 37279067, 2023). "Nuclear localization of STAT3 in head and neck cancers was reportedly associated with a better prognosis." (PMID 28155253, 2017). "Increased phosphorylated STAT3 and Mcl-1 have been often associated with poor prognosis and poor outcome response to chemo- and radiotherapy in various tumors, including head and neck cancer, and inhibition of STAT3 is known to block cancer cell proliferation." (PMID 25605256, 2015). "Given the well-established oncogenic role of STAT3 in both hematological and solid tumors, including head and neck cancers, we sought to determine its functional contribution to fedratinib’s activity." (PMID 41476794, 2025). "For example, depletion of STAT3 stimulates T-cell activity and enhances radiosensitivity in head and neck cancer." (PMID 37564211, 2023). "For example, the results of the first in-human trial examining the effects of STAT3 blockade in head and neck cancers are optimistic, suggesting the possible development of new therapies for cancers insensitive to currently used systemic treatments." (PMID 37371647, 2023). "Targeting LYN, STAT3, and NF-κB showed potential for inhibiting cell motility and tumor growth in EGFRvIII-expressing head and neck cancers 42,43." (PMID 37416766, 2023). "There are potential tumor therapeutic targets in myeloid cells, in which research showed that tolerogenic myeloid cells-expressed gene STAT3 works against the radiotherapy of head and neck cancer." (PMID 36460803, 2023). "The signal transducer and activator of transcription 3 (STAT3) oncogene is a transcription factor with a central role in head and neck cancer." (PMID 34850540, 2022). "SENP3 positively regulates the activation of STAT3 by promoting deSUMOylation of STAT3 in head and neck cancer after the simulation of tobacco." (PMID 36227136, 2022). "SUMOylation of STAT3 negatively regulates its activity by restraining Y705 phosphorylation in the nucleus in head and neck cancer." (PMID 36227136, 2022). "On the other hand, lncRNAs can function as tumor suppressors, such as lncRNA-p21, which inhibits JAK2/STAT3 signal activation and represses STAT3-induced oncogenic potential in head and neck carcinoma." (PMID 35858923, 2022). "A previous study suggests that STAT3 signaling pathways are involved in the maintenance of CSC properties in head and neck cancers." (PMID 34502158, 2021). "We performed immunostaining for phosphorylated STAT3 in tumor cells of five, four, and six cases of gastric, lung, and head and neck cancer, respectively." (PMID 34679602, 2021). "Recent studies have reported that C225, an anti-epidermal growth factor receptor (EGFR) monoclonal antibody, can, in combination with radiation, suppress STAT3 activation results in radiosensitization in head and neck cancer." (PMID 34502158, 2021). "The STAT3 pathway acts as a therapeutic target in head and neck cancers, and we further detected the expression and phosphorylation levels of multiple signal molecules upstream of STAT3." (PMID 32422984, 2020). "It has been demonstrated that IL-6 induces the expression of Snail through JAK/Stat3 signaling in cervical, colorectal or head and neck cancers." (PMID 32570756, 2020).
head and neck cancer (continued). "Transforming growth factor-α (TGF-α)-mediated epidermal growth factor receptor (EGFR) signaling plays a vital role for the activation of STAT3 in some head and neck cancer cell lines." (PMID 30847297, 2019). "Atorvastatin-treated squamous cell carcinoma cell lines, derived from head and neck cancers involving the floor of the mouth and tongue, demonstrated a significant inhibition of phosphorylated STAT3 in connection with reduced metastatic potential." (PMID 30116531, 2018). "A recent study showed a global effect on the gene expression profile of head and neck cancers due to involvement of AP‐1, NF‐κB, and STAT3." (PMID 28155253, 2017). "In head and neck cancers, IL-6 expression and its role in STAT3 activation and tumor growth has been extensively documented." (PMID 28978005, 2017). "In agreement with our study, all these data showed that differentiation is inversely correlated with STAT3 activation in head and neck cancer cells." (PMID 28270740, 2017). "Activation of Src and STAT3 signaling pathway is involved in self-renewal ability and maintaining CICs properties in head and neck cancer." (PMID 27682875, 2016). "Hyaluronan (HA) also induces CD44 binding to Nanog and Stat-3 (a transcription factor) in head and neck cancers (HNSCC, HSC-3 cells line)." (PMID 27070574, 2016). "A recent study finds ergosterol peroxide suppresses the STAT3 and Src activation, and it is found that both Src and STAT3 activations are involved in maintaining CICs properties of head and neck cancer." (PMID 27682875, 2016). "STAT3 is an important component of maintaining self-renewing processes in several malignancy diseases, including head and neck cancer." (PMID 27682875, 2016). "Next, the assessment of EGFr inhibition (cetuximab), with or without the addition of JAK-STAT-3 inhibition (JAK1i), and its effect on STAT-3 protein expression in four human head and neck cancer cell lines was studied." (PMID 26458879, 2015). "Hyperactivation of STAT3 in response to the aberrant activation of upstream receptor signals is frequently observed in a variety of human cancers, including head and neck cancer." (PMID 25605256, 2015). "Data retrieved from Tissue Cancer Genome Atlas head neck cancer dataset suggest DNA copy number of STAT3 significant increase in human HNSCC as compared with control counterpart (P = 7.69E-4)." (PMID 26556875, 2015). "The present study suggests that the combination of inhibitors of EGFr and STAT-3 enhances the effects of radiation in head and neck cancer compared to the use of either agent alone." (PMID 26458879, 2015). "Consistently, in human lung and head and neck carcinomas, STAT3 acetylation and phosphorylation are inversely correlated with SHP-1 expression." (PMID 26667266, 2015). "Signal transducer and activator of transcription 3 (STAT3) has been proven to be critical in tumor cell growth, viability, and metastasis in head and neck cancer among other cancer types." (PMID 24404126, 2014). "It has been reported that Bcl-xL is regulated by EGFR-activated STAT3 to promote survival in head and neck cancer." (PMID 24621885, 2014). "In this study, we selected a novel analog of curcumin (H-4073) because curcumin has been shown to be a potent inhibitor of STAT3 and demonstrate anti-tumor activity in various cancers including head and neck cancer." (PMID 24675768, 2014). "Our institution has recently initiated and completed a biomarker-driven neoadjuvant phase 0 clinical trial of the STAT3 decoy in patients with resectable head and neck cancer." (PMID 24404126, 2014). "Despite the progress of the STAT3 decoy as a therapeutic agent in head and neck cancer, little work has been done to understand how this agent affects other aspects of tumorigenesis such as angiogenesis." (PMID 24404126, 2014).